TCF7L2 (transcription factor 7 like 2)
Diseases named in the same sentence as TCF7L2 in open-access papers (continued):
Sharing a sentence is not in itself a finding about the gene and the disease.
type 2 diabetes (continued). "In maturity onset diabetes of the young, the clinical presentation and treatment needs of patients varies markedly by genotype; whether such clinical heterogeneity by genotype is present for TCF7L2 and type 2 diabetes is unclear." (PMID 17181866, 2006). "The incidence of hypertension, macrovascular disease and type 2 diabetes all increase with age, and prior to the discovery of TCF7L2 it was suggested that a common mechanism might be responsible for all of these pathological states, as these conditions appear to cluster in the same individuals." (PMID 17181866, 2006). "Thus far, the available evidence for TCF7L2 has been from case-control comparisons or intervention trial volunteers, and not representative general populations; data from elderly populations, in whom risks of type 2 diabetes are highest, are scarce." (PMID 17181866, 2006). "In the future, all variants of TCF7L2, KCNQ1, and CDKAL1 could be genotyped to classify clusters of newly diagnosed type 2 diabetes (T2D) in large, multi-centre studies with long-term follow-up." (PMID 41422334, 2025). "The answer lies in the well-known type 2 diabetes marker, TCF4 also known as TCF7L2 (transcription factor 7-like 2)." (PMID 37215099, 2023). "Although this study did not model the Tcf7l2 SNP associated with the risk of type 2 diabetes, based on its potential to utilise the excess glucose pool more efficiently, we suggest that TCF7L2 may be a promising regulator of NAFLD associated with dietary carbohydrates and diabetes." (PMID 36759348, 2023). "We performed in-depth analyses to disentangle the role of adiposity on comorbidity and find evidence that TCF7L2 and TMEM176A exert an effect on type 2 diabetes and osteoarthritis through an alternative biological path." (PMID 37433298, 2023). "The loci identified in the GD GWAS also included known genes affecting both type 2 diabetes and GD—GCKR, MTNR1B, and TCF7L2, as well as the MHC region." (PMID 36553520, 2022). "Similarly, TCF7L2 (gene transcription factor 7-like 2) has been attributed to the pathogenesis of type 2 diabetes mellitus (T2DM) via the Wnt/b-catenin signalling pathway for regulation of adipogenesis." (PMID 36523663, 2022). "Among the hub genes screened, four genes (NEUROG3, TCF7L2, MAP2K5 and RPTOR) were validated as showing the upregulated expression pattern in blood samples in type 2 diabetes cases." (PMID 34830198, 2021). "Of the WNT-annotated SNPs (in genes upstream of TCF7L2), we found, in addition to TCF7L2, the SNPs in NOTCH2 and ZBED3 loci to significantly interact with fiber intake on type 2 diabetes incidence." (PMID 27551309, 2016). "As association between TCF7L2 and type 2 diabetes has highlighted an important role for WNT signaling in type 2 diabetes pathogenesis, we therefore used pathway analysis tools to evaluate whether other type 2 diabetes associated loci might be connected to this pathway." (PMID 27551309, 2016). "SNPs in TCF7L2, NOTCH2, and ZBED3 showed significant interactions with fiber intake on type 2 diabetes incidence (Pinteraction = 0.034, 0.005, 0.017, and 0.002, respectively)." (PMID 27551309, 2016). "Large-scale genome-wide association studies identified loci for type 2 diabetes mellitus (T2DM), including adiponectin (ADIPOQ) gene and transcription factor 7-like 2 (TCF7L2), but few studies clarified the effect of genetic polymorphisms of ADIPOQ and TCF7L2 on risk of T2DM." (PMID 25121131, 2014). "The discovery of TCF7L2 as a global type 2 diabetes (T2D) gene hassparked investigations to explore the clinical utility of its variants forguiding the development of new diagnostic and therapeutic strategies.However, interpreting the resulting associations into function still remainsunclear." (PMID 23617586, 2013). "This has been shown, e.g. for SNPs in TCF7L2 and WFS1 which become more and more relevant during the progression of prediabetes stages towards clinically overt type 2 diabetes." (PMID 22768041, 2012).
type 2 diabetes (continued). "Notably, we could not replicate two other susceptibility SNPs in TCF7L2 (rs11196218 and rs290487), previously reported to be associated with type 2 diabetes in Chinese studies." (PMID 20161779, 2010). "We showed SNPs from seven loci, including GIPR, TCF7L2, MADD, CRY2, GLIS3, PROX1 and SLC30A8, had an effect on type 2 diabetes in our samples." (PMID 21103350, 2010). "We analysed the recently reported type 2 diabetes (T2D) associated polymorphisms in the TCF7L2 gene using a case-control approach, under the hypothesis that TCF7L2 variants should show similar association if diabetes in FCPD is similar to T2D." (PMID 18706099, 2008). "In vitro experiments showed that high glucose toxicity inhibited GLP-1 secretion by enteroendothelial cells and suppressed β-catenin and TCF7L2 levels, suggesting an important role for TCF4 (TCF7L2) in glucose homeostasis and type 2 diabetes development (Hong J.-H." (PMID 40129942, 2025). "Similar to the TCF7L2 locus case, our results suggest that the mechanism through which TMEM176A exerts an effect on osteoarthritis and type 2 diabetes may have contrary directions." (PMID 37433298, 2023). "Intriguingly, although variation in TCF7L2 has been identified as the strongest common genetic determinant of type 2 diabetes, it was not a significant determinant of beta-cell glucose sensitivity but was associated with the early insulin response to an IVGTT." (PMID 32944759, 2021). "In that study, 17 of 40 type 2 diabetes candidate genes were differently methylated, e.g. potassium voltage-gated channel KQT-like subfamily member 1 (KCNQ1) and transcription factor 7-like 2 (TCF7L2)." (PMID 25658116, 2015). "The effect size for rs12571751 in this study (OR = 1.12) was comparable with those for the previously reported type 2 diabetes loci in Japanese populations, but not as large as that of TCF7L2 (OR = 1.51) or KCNQ1 (OR = 1.42)." (PMID 25951451, 2015). "The aim of this study was to investigate the effects of ileal interposition (IT) on glucose and insulin resistance (IR) in type 2 diabetic mellitus (T2DM), and the role of T-cell factor 7-like 2 (TCF7L2), formerly known as TCF4, in the downregulation of hyperglycemia following IT." (PMID 23737909, 2013). "Furthermore, the effect size (OR) of rs5945326-A in the present Japanese sample (OR = 1.39) was larger than that in other Japanese type 2 diabetes loci, except for KCNQ1 and TCF7L2." (PMID 23029454, 2012). "Besides, the effects of previous reported type 2 diabetes and/or fasting glucose loci G6PC2, GCK, GCKR, MTNR1B, DGKB, SLC30A8 and TCF7L2 were also replicated in the meta-analysis." (PMID 21103350, 2010). "In European population, TCF7L2 has not been a risk factor for obesity, but obesity modulates the association between TCf7l2 and risk of type 2 diabetes, additionally, the rs7903146 T allele was more associated with T2D in non-obese individuals than in obese subjects." (PMID 33436000, 2021). "TCF7L2 has to our knowledge not been studied in patients with psoriasis before, but TCF7L2 has previously been connected to known comorbidities of psoriasis such as dyslipidemia, metabolic syndrome, Crohn’s disease and type 2 diabetes." (PMID 31089877, 2019). "TCF7L2 levels are also reported to be increased in β-cells in type-2 diabetics, presumably many of whom do not have the TCF7L2 SNPs, indicating that dysregulation of TCF7L2 may be a more general feature of type-2 diabetes." (PMID 29459424, 2018). "However, PAL did not interact with TCF7L2 genotype on type 2 diabetes incidence (p = 0.46), and the interaction between fibre intake and TCF7L2 genotype on type 2 diabetes incidence remained similar after further adjustment for leisure-time physical activity." (PMID 22782288, 2012).
type 2 diabetes (continued). "In linear regression models, we investigated whether TCF7L2 and CAPN10 variants were associated with phenotypic characteristics among controls without type 2 diabetes, including loge-normalized FPG, waist circumference, BMI, systolic and diastolic blood pressure and urinary albumin." (PMID 24059590, 2013).
diabetes (260 papers, 2006 to 2026). "This variant is known to be associated with the risk of diabetes and TCF7L2 is a component of the Wnt signaling pathway." (PMID 42293346, 2026). "Genotyping revealed high-risk diabetes and CF-modifier variants: rs7903146 TT (TCF7L2) and rs4077468 GG (SLC26A9)." (PMID 42022521, 2026). "Variants of TCF7L2 were found to be associated with different types of diabetes, including T2D in Sudan." (PMID 41376825, 2025). "Findings from the Diabetes Prevention Program and Diabetes Prevention Study reported that interactions with dietary factors can modulate the association between TCF7L2 variants and diabetes risk." (PMID 40170676, 2025). "Given the close genetic association of TCF7L2 with diabetes, we further studied L-KO mice at multiple time points, on different obesogenic diets and after fasting." (PMID 40675550, 2025). "More than 20 genes and their variants have been shown to be associated with diabetes out of which transcription factor 7-like-2 (TCF7L2) rs7903146 (C/T) SNP gene polymorphisms have been frequently involved with T2DM." (PMID 38384655, 2024). "The MHb also expresses Tcf7l2, the most linked gene to diabetes risk, and plays a key role in conveying the risk of developing diabetes after heavy nicotine use." (PMID 39763617, 2024). "TCF7L2 is associated with diabetes and exhibits dependence on KLF-14, where reduced expression increases pre-adipocyte proliferation but impairs lipogenesis." (PMID 38672763, 2024). "Future studies in larger cohorts should be better able to characterize an interaction, if any, with diabetes-associated variation at the TCF7L2 locus." (PMID 39011323, 2024). "Since TCF7L2 genotype in both cohorts was known, we examined the effect of diabetes-associated alleles at both loci on glucose and islet function." (PMID 39011323, 2024). "Previously, we showed that diabetes-associated variation in TCF7L2 is associated with impaired α-cell function." (PMID 39011323, 2024). "We examined the effect of the G-allele at rs10830963 on hormone and substrate concentrations in the people with 2 copies of the diabetes-protective allele (CC) and those with 2 copies of the diabetes-associated allele (TT) in the TCF7L2 locus." (PMID 39011323, 2024). "One of the genes identified in relation to diabetes risk is the transcription factor 7-like 2 gene (TCF7L2)." (PMID 35237941, 2023). "Diabetes duration (OR 0.87, p<0.001) and TCF7L2 rs7903146 T allele (OR 2.93, p=0.047) were significantly associated with the high ICI% group." (PMID 36282337, 2023). "Age at onset, diabetes duration, BMI z score, sex, AA race and TCF7L2 rs7903146 T allele (TT/CT genotypes vs CC genotype) were included as predictors in a multiple logistic regression model." (PMID 36282337, 2023). "If this fact extends to human smokers, it can show the mechanism that deficiency in TCF7L2-dependent signaling leads to an increased risk of tobacco addiction but simultaneously protects against smoking-related diabetes." (PMID 36975496, 2023). "Mutations in the TCF7L2 gene have been associated with increased blood glucose levels, and diabetes." (PMID 36532520, 2022). "While TCF7L2 gene has been shown to affect lipid metabolism, these effects have remained largely unexplored in the context of diabetes risk." (PMID 36263318, 2022). "As part of a series of experiments to measure the effect of diabetes‐associated genetic variation in TCF7L2 on islet cell function, hepatic vein insulin and glucagon concentrations were measured at 2‐minute intervals during fasting and a hyperglycemic clamp." (PMID 35822422, 2022). "Melzer D., Murray A., Hurst A.J., Weedon M.N., Bandinelli S., CorsiA.M., Ferrucci L., Paolisso G., Guralnik J.M., Frayling T.M.Effects of the diabetes linked TCF7L2 polymorphism in a representativeolder population." (PMID 35434484, 2022). "Recent studies have found a significant association between TCF7L2 gene polymorphism and diabetes mellitus." (PMID 36060928, 2022).
diabetes (continued). "T allele of TCF7L2 (rs7903146C/T) polymorphism was considered as a risk allele in diabetes among Iranian cases." (PMID 35366956, 2022). "One study found that the SNP rs7903146 variant of TCF7L2 was associated with a significantly increased stroke prevalence in subjects with diabetes." (PMID 36399471, 2022). "The association of rs7903146 polymorphic form of TCF7L2 gene with enhanced risk of diabetes has been consistently demonstrated from different populations in the world including Asian Indians." (PMID 36263318, 2022). "TCF7L2 gene variant has also been shown to predict future diabetes risk in subjects with impaired glucose tolerance." (PMID 36263318, 2022). "Most observational studies had been conducted on participants with non-diabetes showing that TCF7L2 modified the association between diet (fatty acids and fiber) and insulin resistance." (PMID 36155628, 2022). "Another cohort study concluded that both a parental history of diabetes and the TCF7L2 at-risk variant were associated with a higher incidence of hypertension after controlling for other cardiometabolic risk factors." (PMID 35213968, 2022). "TCF7L2 is a diabetes risk-associated gene which plays a key role in the Wnt-signaling pathway and is shown to be frequently mutated in colorectal cancer and promote cell proliferation." (PMID 35931958, 2022). "In the US Diabetes Prevention Program, TCF7L2 polymorphisms were associated with an increased risk of progression to diabetes, such that the beneficial effects of lifestyle were abolished in the TCF7L2 risk allele group." (PMID 36579607, 2022). "Very few studies have explored its effects on adipogenesis and lipid metabolism as a possible mechanism for the TCF7L2 gene associated risk of development of diabetes." (PMID 36263318, 2022). "Other studies have examined SNPs in genes that are implicated in the development of diabetes by affecting pathophysiological defects such as beta cell failure (e.g. TCF7L2 and CDKAL1)." (PMID 33594477, 2021). "This study showed a positive relationship between TCF7L2 rs7903146 and susceptibility of developing diabetes (OR = 1.61, 95% CI = 1.32–1.96, p < 0.001)." (PMID 34073870, 2021). "Since 2007, polymorphisms of TCF7L2, encoding for transcription factor-7–like 2, are considered to be guilty of β-cells dysfunction and increased risk of diabetes in different ethnic populations." (PMID 34276762, 2021). "Although its expression is critical for adipocyte development, the potential roles of changes in adipose tissue TCF7L2 levels in diabetes risk are poorly defined." (PMID 33068125, 2021). "The consequence of TCF7L2 attenuation is aggravated hyperglycemia, which confers susceptibility to diabetes." (PMID 33919522, 2021). "In particular, the rs7903146 TCF7L2 variant increases the risk of diabetes threefold and decreases the age of onset by 7 years." (PMID 33810109, 2021). "Among them, transcription factor 7-like 2 (TCF7L2) gene variant rs7903146 has attracted significant attention as it is one of the strongest genetic markers of predisposition to diabetes, with the TT genotype increasing disease risk by 40–50%." (PMID 33503923, 2021). "Our findings suggest novel roles for adipokines and incretins in the effects of diabetes-associated variants in TCF7L2, and further illuminate the roles of TCF7L2 in glucose homeostasis and diabetes risk." (PMID 33068125, 2021). "For the first time, the Diabetes Prevention Program and the Diabetes Prevention Study reported that lifestyle intervention reduces diabetic risk among individuals with genetic susceptibility of TCF7L2 risk genotypes." (PMID 33436000, 2021). "The risk allele of rs7903146 interferes with HMGB1 binding, leading to reduced TCF7L2 expression and, therefore, impaired insulin secretion and increased diabetes risk." (PMID 33919522, 2021).
diabetes (continued). "Earlier findings revealed that a TCF7L2 variant increased the risk of incident hypertension or diabetes mellitus; however, the relationship between TCF7L2 and PE is not clear." (PMID 32983644, 2020). "Rs7903146, located in the intronic region of the TCF7L2 gene, is associated with BMI and diabetes in the European population." (PMID 32366963, 2020). "In this study, we investigated the mechanisms underlying the altered hepatic glucose metabolism and enhanced diabetes risk in individuals with the TCF7L2 rs290487 C allele." (PMID 32651957, 2020). "LADA is a hybrid form of diabetes associated with HLA but also with transcription factor 7-like 2 (TCF7L2), which confers the strongest genetic predisposition to T2D." (PMID 30656477, 2020). "This gene encodes a key Wnt signaling pathway effector, and its human homologue transcription factor 7 like-2 (TCF7L2) is a highly diabetes risk gene." (PMID 32326376, 2020). "Gene variants of the transcription factor 7-like 2 (TCF7L2) are associated to the risk of developing diabetes more than any other gene." (PMID 31214120, 2019). "The replicated findings are for variants in ABCC8/KCNJ11 that alters KATP channel function and for the diabetes risk variant in TCF7L2." (PMID 31012484, 2019). "As far as we know, this is the first study that shows altered TCF7L2 gene expression in serum after bariatric surgery, as well as its potential associations with diabetes and decrease in BMI." (PMID 31083695, 2019). "Variants of TCF7L2 are among the strongest risk factors for diabetes, and TCF7L2 has been extensively studied in the context of peripheral metabolism regulation, but studies on its role in brain development and pathologies have been relatively scarce." (PMID 31218672, 2019). "Common variation within the gene encoding transcription factor 7-like 2 (TCF7L2) is now considered to be definitively associated with diabetes susceptibility." (PMID 31312258, 2019). "A previous study by our team showed significant association between an SNP in TCF7L2 and age of onset of diabetes." (PMID 29871606, 2018). "We have already shown that glucose levels interact with what is to date the most important diabetes-associated common SNP in TCF7L2 to affect insulin secretion." (PMID 29138452, 2017). "For other diabetes-related genetic variants, such as TCF7L2, glycemia is an important interacting factor modulating the SNP’s effect." (PMID 29138452, 2017). "The Tcf7l2 gene encodes a key Wnt signalling pathway effector, and its human homologue TCF7L2 is a highly regarded diabetes risk gene." (PMID 28102847, 2017). "Based on their studies, Bodhini et al19 pointed out that association between TCF7L2 gene polymorphism and DN was mediated through diabetes." (PMID 26986145, 2016). "A genetic risk score based on the diabetes risk alleles TCF7L2 rs7903146, KCNQ1 rs163184, KCNQ1 rs2237892, GIPR rs10423928 and WFS1 rs10010131 also showed a nominally significant interaction with coffee intake (p = 0.005)." (PMID 27623947, 2016). "The present findings warrant further studies on the molecular circuitry governing Tcf7l2 activity in the embryonic pancreas and its potential implications for diabetes susceptibility." (PMID 26771085, 2016). "Transcription factor 7-like 2 (TCF7L2) is a risk factor of diabetes that is linked to a large variety of diseases." (PMID 27721485, 2016). "Although genetic variants in TCF7L2 gene likely increase the risk of diabetes, the variant allele of TCF7L2 rs6585194 and rs7094463 elicited protective effects against diabetes." (PMID 27465520, 2016). "This study aimed to investigate the possible association between diabetes susceptibility gene transcription factor 7-like 2 (TCF7L2) and gestational diabetes mellitus (GDM) in a Chinese Han population." (PMID 27465520, 2016). "In conclusion, our meta-analysis identified an association between T genotype of TCF7L2 rs7903146 with lower TG level in subjects with diabetes." (PMID 26576435, 2015).